INS (insulin)
Diseases named in the same sentence as INS in open-access papers (continued):
Sharing a sentence is not in itself a finding about the gene and the disease.
diabetes (continued). "This in silico study revealed that the six known compounds have good inhibitory action to T2DM targets, namely, RBP4 and AKR1B1, which contribute in improving insulin sensitivity and prevent diabetes complication, respectively." (PMID 35807241, 2022). "Understanding these lung responses to insulin is crucial in the application of insulin treatments, including inhalants and injectables, and understanding the pathogenesis of infection in the lungs of patients with diabetes mellitus." (PMID 35273609, 2022). "The FLI < 30 group had a higher proportion of patients with a diabetes duration ≥ 5 years, number of OHAs ≥ 2, and insulin use than the other groups." (PMID 36474232, 2022). "Diabetes mellitus (DM) is a chronic medical condition in which the body either produces too little insulin from pancreatic islets or lacks effective access to insulin." (PMID 35840989, 2022). "All patients with hyperglycemia were treated with intravenous insulin according to the Standards of Medical Care in Diabetes 2021 guidelines." (PMID 35629227, 2022). "Diabetes, a metabolic disorder, is characterized by hyperglycemia, insulin secretion defects, and insulin insensitivity." (PMID 36005597, 2022). "We utilized immunoglobulin (Ig) heavy chain (VH125) mouse models in which high-affinity insulin-reactive B cells (IBCs) were previously shown to be anergic in diabetes-resistant VH125.C57BL/6-H2g7 and activated in VH125." (PMID 36275764, 2022). "This suggests that the insulin reduction carried out at camp was insufficient, despite insulin being reduced by almost 20% on average in line with suggestions for insulin dose adaption at diabetes camps." (PMID 36553394, 2022). "In conclusion, these data reveal the unique effects of C646 in activating insulin signaling in patients with obesity and diabetes." (PMID 35074429, 2022). "Insulin therapy in diabetes patients often increases body weight and leads to visceral fat accumulation." (PMID 36224294, 2022). "The planned study is an ongoing open-label randomised controlled trial in which adults living with T2DM treated with insulin will be randomised 1:1 to the use of this diabetes application versus current standard care." (PMID 35710428, 2022). "Assessing the relationship between diabetes and obesity, in our study, it is possible to observe that in childhood and adolescence, β-pancreatic cells increase their production of insulin as a compensatory mechanism, while glucose tolerance remains normal." (PMID 35703718, 2022). "The pathophysiology of the onset of diabetes is multifactorial, but substantially lies in the increased IR and gluconeogenesis and decreased insulin production." (PMID 36551851, 2022). "These methods include chemical and physical enhancers, both of which provide improved diabetes care through improvements in efficacy and safe delivery of insulin into the systemic circulation." (PMID 35890301, 2022). "It is challenging for a person with double diabetes to achieve reasonable glycemic control, avoid insulin-related weight gain, and prevent hypoglycaemia." (PMID 36415365, 2022). "Thiamine or vitamin B1 is a coenzyme involved in the metabolism of sugars; it is essential for the synthesis and secretion of insulin, and its level decreases in diabetes." (PMID 35725834, 2022). "Current treatments for the cardiorenal complications of diabetes are based on the control of blood glucose levels, mainly with metformin and sulfonylureas in type 2 diabetes mellitus and insulin mainly in type 1 diabetes." (PMID 36289741, 2022). "Nuts also have a low glycemic index owing to a higher concentration in fat, leading to a lower contribution of glucose to the energy supply; therefore, less insulin is required, and this should favor control of diabetes." (PMID 35458240, 2022). "In the early 1930s it was noticed that people with diabetes responded differently to insulin, enabling the differentiation between insulin-insufficient and insulin-sensitive subgroups." (PMID 35994083, 2022).
diabetes (continued). "Exercise training is a key therapeutic strategy in diabetes that functions by increasing insulin sensitivity and providing glycemic control." (PMID 36012137, 2022). "The increased glycation of insulin has a vital role in the pathogenesis of numerous disease, such as diabetes, leading to the formation of advanced glycation end products (AGEs)." (PMID 36422117, 2022). "Patients suffering from type 2 diabetes mellitus exhibit significant hyperglycemia and decreased insulin secretion." (PMID 36506561, 2022). "Diabetes mellitus is a group of metabolic diseases characterized by hyperglycemia resulting from defects in insulin secretion, a defect in insulin action, or a combination of both." (PMID 35592526, 2022). "Among them, ACDC has been shown to exhibit anti-diabetic, anti-atherogenic, and anti-inflammatory effects, and it is also an insulin sensitizer, thus revealing it as a novel therapeutic factor to be targeted for diabetes and MetS." (PMID 36235679, 2022). "Eventually, this process leads to insufficient insulin secretion and thus to hyperglycaemia in people with diabetes." (PMID 36431053, 2022). "Recent studies have also shown that there is a redifferentiation of β-cells via intensive insulin therapy in a diabetes mice." (PMID 35562869, 2022). "In the current study, injection of STZ increased blood glucose, dysregulated lipid profile, decreased the amount of insulin and leptin, and developed diabetes." (PMID 36479221, 2022). "Various approaches, such as insulin pills and the utilization of sugar-free food, are adopted to control diabetes and obesity." (PMID 36235263, 2022). "For example, diabetic patients use blood glucose readings to control insulin infusion pumps, providing a more physiologically accurate way to manage diabetes than intermittent finger prick readings and bolus insulin injections." (PMID 35040037, 2022). "Type-1-Diabetes, also known as Juvenile Diabetes, is an autoimmune condition in which the body's immune system destroys the insulin-producing beta cells in the pancreas." (PMID 36351917, 2022). "P5 was compared against exendin‐4 in a variety of mouse models of diabetes, showing an unusual pharmacodynamic profile including greater acute anti‐hyperglycaemic efficacy than exendin‐4 but reduced insulin secretion and unaffected insulin sensitivity." (PMID 33880754, 2022). "Manganese supplementation has also been shown to improve insulin secretion in mice, and also manganese-dependent superoxide dismutase has shown to protect against oxidative DNA damage in mitochondria in diabetes." (PMID 35789593, 2022). "β-cell dysfunction, which means the inability of the pancreas to produce enough insulin in response to glucose stimulation, is a typical pathological mechanism in type 2 diabetes mellitus (T2DM)." (PMID 35739484, 2022). "Overexpression of Pdx1 in liver cells by CRISPR/Cas9-mediated TGA system (used with dgRNA that deactivates Cas9) led to their transdifferentiation into insulin-secreting cells in a mouse STZ-induced T1D model of diabetes." (PMID 36246880, 2022). "There was a trend toward increased symptomatic periradicular disease in patients with diabetes who received insulin, as well as flare ups in all patients with diabetes." (PMID 35888650, 2022). "The glucose values are provided at 5-min intervals and can be used for diabetes treatment decisions or can be acted upon by devices from other manufacturers, such as automated insulin delivery systems or multidose memory insulin pens." (PMID 35157505, 2022). "Lastly, the induction of the adiponectin gene by KLF9 is clearly of follow-up interest from the related contexts of tumor suppression and insulin sensitivity (anti-diabetes)." (PMID 35406507, 2022). "For example, the cognitive ability of the person was identified as a barrier to managing diabetes with insulin if the person was unable to understand and retain information about how to do it." (PMID 35983585, 2022).
diabetes (continued). "Diabetes mellitus (DM) is a metabolic disease whose main manifestation is chronic hyperglycemia, combined with defective insulin secretion or action, and is one of the major diseases endangering human health, and its prevalence is exploding and younger." (PMID 35719682, 2022). "Here, we show that Stx2 acts to assist this precise tuning of insulin secretion in β-cells, including in diabetes." (PMID 36316316, 2022). "In the open Artificial Pancreas System movement, diabetes patients hacked together an artificial pancreas system from their glucose monitors and insulin pumps, years before such a system was approved by the United States Food and Drug Administration (US FDA)." (PMID 36632334, 2022). "The results indicate it is crucial that people with intellectual disabilities receive appropriate support from family, carers, support workers and healthcare professionals to optimise their ability to manage their diabetes with insulin." (PMID 35983585, 2022). "The tested variables included age, sex, body mass index (BMI), creatinine clearance, diabetes on insulin or oral treatment, hypertension, and LV mass index." (PMID 35213562, 2022). "Diabetes is a chronic disease characterized by an elevation of blood glucose levels as a result of insufficient insulin for the body’s needs." (PMID 35303528, 2022). "Other less selected criteria included the risk of hypoglycemia, the patient’s work schedule and lifestyle factors, the availability of nurses, diabetes educators, and others to follow the insulin treatment, and the cost of insulin." (PMID 36554673, 2022). "Because access to insulin and self-monitoring are essential components of diabetes management, it is critical to support better planning, choose cost-effective options, and simplify the selection of priority items." (PMID 35854336, 2022). "Misperceptions concerning the severity and proper management of diabetes can slow down the energetic participation of the patient in the treatment, such as unwillingness to start insulin therapy." (PMID 37274843, 2022). "INS-related monogenic diabetes ranges from milder forms that benefit from diet to more severe clinical situations, even with ketoacidosis, with variable age of onset." (PMID 35769090, 2022). "If a person with diabetes had low mood or was not motivated to do their own injections and/or check blood glucose levels, this affected their ability to manage their diabetes with insulin." (PMID 35983585, 2022). "The RRRs for percentage of glucose values in range in both GC-induced diabetes and preexisting diabetes were significantly higher with all three insulin treatments." (PMID 34986826, 2022). "Type 2 diabetes mellitus is a complex metabolic disease which is characterized by high blood plasma glucose levels due to insufficient production of insulin, defective signaling, and inefficient insulin action in the body." (PMID 36079819, 2022). "Type 1 diabetes mellitus (T1DM) is an autoimmune disorder in which the pancreatic beta cells responsible for insulin production are destroyed." (PMID 36185927, 2022). "They utilized their frequent contact with patients to provide individualized diabetes education including the use of insulin with food insecurity and substance use." (PMID 36992789, 2022). "Insulin-requiring diabetes management is commonly aided by CGM, which yields longitudinal glucose data and assists clinicians and researchers to understand various factors of glucose variability." (PMID 35565875, 2022). "Administration of specific prebiotics can prevent the development of high-fat diet-induced diabetes and result in improved glucose tolerance, restored insulin secretion, decreased intestinal endotoxin levels and alleviated inflammatory response." (PMID 35008906, 2022). "Most respondents reported that they were able to self-manage their diabetes at home and just less than half had insulin treated diabetes." (PMID 36068537, 2022).
diabetes (continued). "Diabetes is characterised by raised blood glucose levels (hyperglycaemia) resulting from partial or total insufficiency in the insulin hormone." (PMID 35983585, 2022). "It has made it possible for the two critical characteristics of diabetes (insulin resistance and pancreatic-cell dysfunction) to be combined under a single Foxo-dependent methodology." (PMID 36381916, 2022). "One hundred seventy-six individuals suffered from osteoporosis, while 103 had diabetes mellitus (60 of which were insulin-independent and 43 insulin-dependent)." (PMID 35138487, 2022). "The main reported medium-term complications were pseudocyst formation (n=9, 10%), diabetes requiring insulin therapy at 1 year (n=4, 4%) and maldigestion (n=1, 1%)." (PMID 36053577, 2022). "Pancreatic insulin was discovered a century ago, and this discovery led to the first lifesaving treatment for diabetes." (PMID 36244663, 2022). "In patients with ESRD and diabetes, impaired insulin clearance and renal gluconeogenesis render patients vulnerable to low blood sugar levels as demonstrated by hypoglycemia accounting for 3.6% of all ESRD-related admissions." (PMID 36264931, 2022). "Following years of research, we have come to know that type 1 diabetes mellitus (T1DM) is associated with the destruction and dysfunction of pancreatic β-cells, causing a shortage of systemic insulin supply." (PMID 35890301, 2022). "We report a 56-year-old woman insulin-treated patient with type 2 diabetes mellitus who developed new-onset, sharply well-demarcated erythematous scaly plaques at the insulin injection sites consistent with Koebner phenomenon." (PMID 37908249, 2022). "First, concerning information needs, most respondents reported that they needed more information relevant to their daily lives and more Arabic language websites that provide simple diabetes, insulin, and CHO counting information." (PMID 38515508, 2022). "The results indicated that, on the basis of current diabetes guidelines, basal insulin was prescribed more often than premixed insulin at initiation." (PMID 35023626, 2022). "Insulin sensitivity decreases with age and can lead to insulin resistance and type 2 diabetes mellitus." (PMID 34936049, 2022). "The chronic hyperglycemia seen in diabetes is precipitated due to abnormalities in insulin secretion, insulin action, or a combination of both in the form of insulin resistance." (PMID 35872997, 2022). "Amino acid-induced insulin signal transduction damage and G protein coupled receptor involvement lead to insulin resistance and type 2 diabetes mellitus." (PMID 36618372, 2022). "The strength of our study is the actual power of the sample size which is large enough to reach a significant correlation of the efficacy of the self-management total score on the HbA1c value in type 2 diabetes mellitus patients treated with insulin." (PMID 36292529, 2022). "Understanding how food choices are made during hypoglycemia is fundamental to improve treatment in people with diabetes requiring insulin." (PMID 36351679, 2022). "Predicting glucose amounts based on food and insulin intake is a hard task that should be done daily for cases with diabetes." (PMID 36572938, 2022). "It is proposed that diabetes induces changes in glucose metabolism, vascular structure, function and insulin signalling." (PMID 35101010, 2022). "Different insulin analogues used to treat diabetes are also difficult to distinguish by immunoassay, due to antibody cross-reactivity." (PMID 36242807, 2022). "Whereas iron deficiency has been shown to be beneficial for coronary response, endothelial dysfunction, insulin secretion, insulin action, and metabolic control in type 2 diabetes mellitus." (PMID 36482994, 2022). "The PI3K pathway is a major player in diabetes through its induction by insulin and effects on metabolism." (PMID 35328698, 2022).
diabetes (continued). "Diabetes is defined by fasting hyperglycemia while plasma insulin levels were found poorly correlated with plasma glucose levels in a segregating F2 population derived from Apoe−/− mouse strains that developed type 2 diabetes on the Western diet." (PMID 36078077, 2022). "Regarding type 2 diabetes mellitus, it has been reported that resveratrol improves insulin sensitivity and reduces blood glucose in cell cultures and animal models." (PMID 36687699, 2022). "The effectiveness of these drugs on diabetes and obesity is primarily due to the regulation of glycemia, insulin, and glucagon secretion." (PMID 35054924, 2022). "The incidence of diabetes in HD patients is seven times higher than that of normal diabetes, whose pathological features are reduced insulin secretion and increased insulin resistance." (PMID 35154571, 2022). "High blood glucose levels and disrupted insulin regulation in patients with diabetes lead to vascular endothelial damage and oxidative stress in the body, which damage blood vessels and neurons and lead to the formation of atherosclerosis." (PMID 35800241, 2022). "Diabetes mellitus (DM) is a chronic disease characterized by hyperglycemia due to obesity and defects in insulin action." (PMID 35677892, 2022). "Insulin, which is the first-line treatment of diabetes during pregnancy, was by far the most frequently claimed anti-diabetic drug during pregnancy (389.8/10,000)." (PMID 35162474, 2022). "Nevertheless, diabetes-related health conditions can be prevented with pharmacological treatment and insulin." (PMID 36438767, 2022). "The vast majority of indices in NGT and pre-diabetes correlate significantly with clamp-derived GLP1-stimulated insulin secretion index." (PMID 36100292, 2022). "Although some fish species were used as models for diabetes research, the effects of GH on insulin and glucose catabolism and anabolism in these models remain to be clarified." (PMID 36561570, 2022). "Women with diabetes, especially those on insulin were more likely to give birth to babies with macrosomia in two of the three studies rated moderate." (PMID 35387600, 2022). "We observed that the insulin treatment group had patients with higher BMIs before pregnancy (Z = −2.281, P = 0.023) and a higher proportion of pregnant women with diabetes (χ2 = 20.618, P < 0.001) and fatty liver (χ2 = 4.333, P = 0.037) than the control group." (PMID 36405614, 2022). "According to the definition, diabetes mellitus (DM) represents a group of metabolic disorders characterized by chronic hyperglycemia, which stems from impaired production or action of insulin." (PMID 36140292, 2022). "The treatment of diabetes-induced rats with β-Caryophyllene restored the altered levels of blood glucose, serum insulin as well as lipid parameters." (PMID 37693084, 2022). "Diabetes mellitus (DM) is a chronic disease with a metabolic disorder characterized by hyperglycemia, resulting from insufficient insulin secretion in the body or insulin resistance (IR)." (PMID 36458172, 2022). "Insulin resistance, aberrant insulin secretion, and hepatic glucose production, as well as poor lipid metabolism, are all factors that contribute to diabetes." (PMID 36557843, 2022). "Our findings support this, as all six scores effectively detect diabetes in the insulin resistant group, the group that also had the highest prevalence of obesity." (PMID 36211668, 2022). "Decreased insulin sensitivity and impaired insulin secretion play a major role in the pathogenesis of diabetes." (PMID 36118835, 2022). "In this case, the prolonged NGN3 stimulation by cytokines in a chronic inflammatory environment such as diabetes appears to retain cells in an undifferentiated condition and prevent the formation of insulin positive ductal cells." (PMID 34542797, 2022).